TRBJ2-7 (T cell receptor beta joining 2-7)
Description:
J region of the variable domain of T cell receptor (TR) beta chain that participates in the antigen recognition. Alpha-beta T cell receptors are antigen specific receptors which are essential to the immune response and are present on the cell surface of T lymphocytes. Recognize peptide-major histocompatibility (MH) (pMH) complexes that are displayed by antigen presenting cells (APC), a prerequisite for efficient T cell adaptive immunity against pathogens. Binding of alpha-beta TR to pMH complex initiates TR-CD3 clustering on the cell surface and intracellular activation of LCK that phosphorylates the ITAM motifs of CD3G, CD3D, CD3E and CD247 enabling the recruitment of ZAP70. In turn, ZAP70 phosphorylates LAT, which recruits numerous signaling molecules to form the LAT signalosome. The LAT signalosome propagates signal branching to three major signaling pathways, the calcium, the mitogen-activated protein kinase (MAPK) kinase and the nuclear factor NF-kappa-B (NF-kB) pathways, leading to the mobilization of transcription factors that are critical for gene expression and essential for T cell growth and differentiation. The T cell repertoire is generated in the thymus, by V-(D)-J rearrangement. This repertoire is then shaped by intrathymic selection events to generate a peripheral T cell pool of self-MH restricted, non-autoaggressive T cells. Post-thymic interaction of alpha-beta TR with the pMH complexes shapes TR structural and functional avidity.
Synonyms: TRBJ27; TCRBJ2S7
Gene: T-cell receptor joining (J) gene on chromosome 7 (142,797,456 to 142,797,502, forward strand). Ensembl gene ENSG00000211771.
Subcellular location: Cell membrane
Gene Ontology:
Cellular component: plasma membrane
Diseases named in the same sentence as TRBJ2-7 in open-access papers:
TRBJ2-7 is named in the same sentence as 3 diseases in open-access papers, as found by Europe PMC text mining. Sharing a sentence is not in itself a finding about the gene and the disease. The quoted sentences say what the papers report.
diabetic neuropathy (1 paper, 2025). A chronic, pathological complication associated with diabetes mellitus, where nerve damages are incurred due to diabetic microvascular injury involving small blood vessels that supply these nerves, resulting in peripheral and/or autonomic nerve dysfunction. "In addition, further research is needed to explore the roles of specific biomolecules implicated in diabetic neuropathy development, such as SLC30A1, TRBJ2‐7, OLFM1, TCF7L2, MCF2L, CEP295NL, CEACAM22P, TSHZ2, and PDZD4." (PMID 40692573, 2025).
Sjögren's syndrome (1 paper, 2025). "For the β chain, many V/J genes, which were highly expressed in cachexic HCC mice, were associated with type I diabetes, such as Trbv1 [S18,19], Trbv13‐2 [S19], Trbj2‐7 [S19,20] and with Sjögren's syndrome, such as Trbv3 [S21], Trbv16 [S22] and Trbj2‐2 [S22]." (PMID 40665793, 2025).
TRBJ2-7 also shares sentences with these, for which no sentence is quoted: type I diabetes (1 paper).